YIPF3 (Yip1 domain family member 3)
Description:
Involved in the maintenance of the Golgi structure. May play a role in hematopoiesis.
Synonyms: C6orf109; KLIP1; DKFZp566C243; dJ337H4.3; FinGER3; Yip5b; YIPFbeta2
Tractability: Antibody: UniProt places it where antibodies can reach, with medium confidence; UniProt predicts a signal peptide or a membrane-spanning region; its Gene Ontology location is reachable by antibodies, with medium confidence. PROTAC: ubiquitination databases record sites on it; its protein half-life has been measured.
Gene: Protein-coding gene on chromosome 6 (43,511,821 to 43,516,985, reverse strand). Ensembl gene ENSG00000137207.
Subcellular location: Cell membrane; Cytoplasm; Golgi apparatus, cis-Golgi network membrane
Subcellular location (Human Protein Atlas): Golgi apparatus; Nucleoplasm
Gene Ontology:
Molecular function: protein binding
Cellular component: Golgi apparatus; transport vesicle; cytoplasm; plasma membrane
Genetic constraint (gnomAD): Loss-of-function variants: 18 observed, 42.61 expected, observed/expected ratio (o/e) 0.42, 90% interval 0.29 to 0.63. The upper end of that interval is the gene's LOEUF score, 0.63, which puts it in group 2 of 6, group 1 being the genes least tolerant of losing a copy. Missense variants: 406 observed, 469.25 expected, observed/expected ratio (o/e) 0.87, 90% interval 0.8 to 0.94. Synonymous variants: 190 observed, 184.36 expected, observed/expected ratio (o/e) 1.03, 90% interval 0.92 to 1.16.
Homologues: Orthologues: chimpanzee YIPF3 (100% identical), pig YIPF3 (97% identical), dog YIPF3 (97% identical), rabbit YIPF3 (97% identical), mouse Yipf3 (96% identical), guinea pig YIPF3 (95% identical), rat Yipf3 (95% identical), macaque YIPF3 (89% identical), tropical clawed frog yipf3 (77% identical), zebrafish yipf3 (76% identical), Caenorhabditis elegans Y53C12A.3 (29% identical). Paralogues in human: DTWD1 (11% identical).
Diseases named in the same sentence as YIPF3 in open-access papers:
YIPF3 is named in the same sentence as 1 disease in open-access papers, as found by Europe PMC text mining. Sharing a sentence is not in itself a finding about the gene and the disease.
YIPF3 shares sentences with these, for which no sentence is quoted: uterine serous carcinoma (1 paper).